ERBB2 (erb-b2 receptor tyrosine kinase 2)
Diseases named in the same sentence as ERBB2 in open-access papers (continued):
Sharing a sentence is not in itself a finding about the gene and the disease.
breast cancer (continued). "Increased migration of p140Cap-silenced cells was also observed in MDA-MB-453 breast cancer cells, another model of ERBB2 gene amplification relevant to human breast cancer." (PMID 28300085, 2017). "NR1D1 circadian transcription factor has found to be co-amplified with the receptor ERBB2 in “HER2-positive breast cancer” and probably contribute to the aggressiveness of this malignancy." (PMID 28177907, 2017). "In the same decade, trastuzumab was approved for the treatment of breast cancer patients with amplification of ERBB2 (human epidermal growth factor receptor 2, also known as HER2/neu)." (PMID 28685150, 2017). "Limited efficiency coupled with off target adverse effects have been seen in CAR-T cells targeting solid tumours, including renal carcinoma, neuroblastoma, ovarian cancer, and even ERBB2 positive breast cancer." (PMID 28885562, 2017). "Genome alteration-matched treatment of breast cancer to target amplification of human epidermal growth factor receptor 2 gene (Erb-B2 receptor tyrosine kinase 2, ERBB2 also known as HER2) is an example of a successful gene-targeted therapy." (PMID 28474673, 2017). "ErbB2 expression in early breast cancer can predict tumor aggressiveness and clinical outcomes in large patient populations." (PMID 29089571, 2017). "ErbB2 overexpression is detected in approximately 20% of breast cancers and is correlated with poor survival." (PMID 28442738, 2017). "When ErbB2-overexpressing breast cancer cells were treated with the trastuzumab, the autophagy protein ATG12 was differentially upregulated." (PMID 28338617, 2017). "In patients with triple-negative breast cancer, MFG-E8 promotes breast cancer progression through the p63 pathway; but in estrogen receptor- and erbB2-positive breast cancers, MFG-E8 serves a suppressive function." (PMID 28292326, 2017). "Previously, it was reported that ErbB2 and IGF1R can heterotrimerize with ErbB3 to enhance receptor activation and downstream signaling responses in ErbB2-overexpressing breast cancer cells." (PMID 28947975, 2017). "To this end, we investigated the anti-cancer mechanisms that are induced by AZD4547 in ErbB2-overexpressing breast cancer models." (PMID 28900173, 2017). "Clinically, breast cancer is usually categorized based on the expression of specific receptors, including estrogen receptor (ER), progesterone receptor (PR), and human epidermal growth factor receptor 2 (HER2)/neu (also known as ERBB2)." (PMID 29108265, 2017). "Functionally, ERRF indeed sensitizes ERBB2 positive breast cancer to the therapeutic effects of lapatinib." (PMID 28415602, 2017). "ERBB2 amplification and overexpression have been shown to possess a prevalence of 15–25% in breast cancer patients." (PMID 28885562, 2017). "Erbb4 appears to be an oncogene in breast cancers, and Erbb2 has been suggested to help Erbb4 carry out the oncogenic activities." (PMID 28212608, 2017). "ErbB2/Her2 oncoprotein is overproduced by a significant fraction of breast cancers and promotes anchorage-independent tumor cell growth by poorly understood mechanisms." (PMID 29285258, 2017). "In this research, we demonstrate, for the first time, that miR-1268b is involved in the regulation of breast cancer chemosensitivity and apoptosis by targeting ERBB2." (PMID 29163776, 2017). "Our data from ErbB2-overexpressing breast cancer cells and syngeneic tumor grafts corroborate that phenformin can block EMT, as evidenced by the upregulation of E-cadherin and concurrent downregulation of EMT markers." (PMID 28947975, 2017). "An inverse correlation between ERRF expression and ERBB2 status was also evident in an expression profiling study of 2000 breast cancer specimens." (PMID 28415602, 2017).
breast cancer (continued). "Treatment TNBC and ERBB2+ breast cancer cells with neratinib also reduced the expression of p62 SQMT1, LAMP2, HDAC6, DRP-1, mitochondrial HSP70, HSP70, HSP90 and GRP78." (PMID 29163826, 2017). "Understanding ErbB2 interactomics and its regulation is a key factor to improve therapeutical approaches and overcome trastuzumab resistance, a clinical phenomenon that occurs in 66 to 88% of ErbB2-possitive metastatic breast cancers." (PMID 28306722, 2017). "It was showed that Stat3 binds to its response elements at the HER2(ErbB-2) promoter to upregulate HER2(ErbB-2) transcription in breast cancer, highlighting Stat3 general role as upstream regulator of HER2(ErbB-2) expression in breast cancer." (PMID 28881721, 2017). "Our previously reported H2-18, an anti-ErbB2 antibody, potently induced programmed cell death in trastuzumab-resistant breast cancer cells." (PMID 28881779, 2017). "Preclinical studies have shown that lapatinib inhibits cell proliferation in EGFR and/or ErbB2-overexpressing breast cancer cell lines, even in trastuzumab-resistant cells." (PMID 28938602, 2017). "In this respect, C1orf64 log2 median expression values were analyzed to assess a differential expression of C1orf64 for histology type, tumor grade, ER status, ErbB2 status, triple negative (TN) status, and outcome across twenty-two breast cancer datasets." (PMID 28915724, 2017). "We successfully showed that these genetically modified CD3+ cells were able to specifically target and induce apoptosis in the ERBB2 overexpressing breast cancer cell line, SKBR3." (PMID 28885562, 2017). "We took advantage of the NeuT mouse model of mammary breast cancer, and of human ERBB2 breast cancer cells, to address the role of p140Cap protein in the ERBB2-related breast cancer disease." (PMID 28300085, 2017). "Consistently, phenformin induced similar changes in the expression of the EMT markers in BT474 cells, another ErbB2-overexperssing human breast cancer cell line." (PMID 28947975, 2017). "Here, we demonstrated that miR-1296-5p decreases the expression level of ERBB2 to inhibit the cell proliferation in ERBB2-positive breast cancer." (PMID 29089858, 2017). "Breast cancer is the most common cancer among women and 30% will be diagnosed with an ErbB2-positive cancer." (PMID 28783168, 2017). "To investigate the molecular mechanism of miR-1268b in enhancing chemosensitivity of breast cancer, we explored the potential target gene of miR-1268b by softwares of miRWalk and RNAhybrid, and ERBB2 was selected for further confirmation." (PMID 29163776, 2017). "Treatment with trastuzumab induced a slight growth reduction in SKBR-3 cells cultured in 2D, whereas proliferation was strongly inhibited in the 3D spheroids mirroring the clinical benefit of trastuzumab for ErbB2-positive breast cancer patients." (PMID 29296175, 2017). "Here we report the formation of circular dorsal ruffles (CDRs) upon treatment of the ERBB2-overexpressing breast cancer cell lines SK-BR-3 and ZR751 with Trastuzumab, a therapeutic humanized monoclonal antibody directed against ERBB2." (PMID 28947957, 2017). "ErbB2 has been intensively studied in breast cancer and is known to be overexpressed in other cancer types as well, including urinary bladder, lung, digestive tract, endometrial and cervical cancer." (PMID 28417948, 2017). "We previously reported that ERRF expression positively correlates with ER and PR statuses but negatively associated with ERBB2 status, and knockdown of ERRF inhibits the proliferation and tumorigenesis of ER- and PR-positive breast cancer cells." (PMID 28415602, 2017).
breast cancer (continued). "Based on our previous work and the premise that the effects of phenformin on individual breast cancer subtypes have not been fully explored, it is intriguing to explore the effects of phenformin on ErbB2-overexpressing breast cancer models." (PMID 28947975, 2017). "In our study, we report growth inhibition, targeted suppression of putative MaSC/CSC-enriched populations, and modulation of cell stemness, as measured by various analyses, in cellular, syngeneic, and transgenic models of erbB-2-overexpressing breast cancer." (PMID 28193239, 2017). "Lapatinib, a dual inhibitor of EGFR and ErbB2 tyrosine kinases, induced autophagic cell death in ErbB2 overexpressing breast cancer cells, human hepatoma cells, and acute myeloblastic leukemia." (PMID 28338617, 2017). "Overexpression of ERBB2 through gene amplification is noticed in breast cancer (30%) and even in other malignancies, correlating with poor disease prognosis." (PMID 29119846, 2017). "Following systemic administration, ErbB2 expression was visualized in vivo from human xenograft breast cancers implanted in nude mice." (PMID 29089571, 2017). "Although no clinical evidence is currently available in terms of their actionability in PTs or sarcomas, clinical data support the potential targeting of these AKT, ERBB2, and PIK3CA hotspot mutations in breast cancer (OncoKB level of evidence 3A)." (PMID 29043292, 2017). "Several studies have also reported transient activation of ERK1/2 in HER2-overexpressing breast cancer cells by the transactivation of the ErbB2 (HER2) via GDF15-triggered TGFβ receptor-Src activation." (PMID 28206960, 2017). "Clinically, the overexpression of erbB-2 is correlated with poor survival and short time to relapse rates in breast cancer patients." (PMID 28460461, 2017). "As suggested by the critical role of CIP2A in lapatinib-induced inhibition of ErbB2-overexpressing breast cancer cells, we further demonstrated that CIP2A deregulation was associated with lapatinib resistance." (PMID 28938602, 2017). "In this study, we investigated the effect of CIP2A on lapatinib-induced anti-cancer activities and resistance in ErbB2-overexpressing breast cancer cells." (PMID 28938602, 2017). "Those cells that survive after ErbB2 loss display resistance to trastuzumab, an anti-ErbB2 antibody used for ErbB2-positive breast cancer treatment." (PMID 29285258, 2017). "ErbB2/Her2, a member of the human epidermal growth factor receptor family, is highly overexpressed in 20–30% of all breast cancer cases." (PMID 27791982, 2017). "erbB-2-overexpressing breast cancers comprise nearly one-third of all breast cancer cases and are refractory to many therapeutics as drug-resistance often arises." (PMID 28061785, 2017). "In another study the inhibitory effect of EGCG on ErbB2 and ErbB3 overexpressing breast cancer cells was evaluated." (PMID 28286519, 2017). "In particular, amplification of ErbB2/HER2 in breast cancer correlates with disease progression, poorer prognosis, and recurrence." (PMID 28174229, 2017). "Another subtype of breast cancer is characterized by amplification of oncogene HER2 (also known as ERBB2 or EGFR2), a tyrosine kinase receptor, which stimulates cell proliferation and inhibits apoptosis." (PMID 29090014, 2017). "Nowdays, new treatments like anti-ERBB2 targeted therapies have radically improved the patients’ survival for ERBB2 positive breast cancers." (PMID 29163776, 2017). "MMTV-erbB-2 transgenic mice are a clinically relevant model of erbB-2-overexpressing breast cancers with a defined genetic background and tumors forming at approximately 35 weeks of age." (PMID 28061785, 2017).
breast cancer (continued). "We found that metformin significantly inhibited cell proliferation and the stemness of erbB-2-overexpressing breast cancer cell lines." (PMID 28193239, 2017). "MiR-21 signaling sustains epithelial-to-mesenchymal transition (EMT) in ERBB2-positive breast cancer." (PMID 28160563, 2017). "We found that an increase in the cell density within a three-dimensionally grown mass of breast cancer cells strongly blocks the expression and phosphorylation of the Mek substrate Erk and essentially eliminates ErbB2 from the cells." (PMID 29285258, 2017). "TRPS1 over-expressed in the breast cancer cell lines with high level of ERBB2 expression, while under-expressed in those with low level or negative ERBB2 expression (p=0.003)." (PMID 28423734, 2017). "All in all, our in vitro and in vivo data support phenformin as a promising candidate for ErbB2+ breast cancer treatment and provides the foundation for future studies on the anti-cancer mechanisms of biguanide drugs." (PMID 28947975, 2017). "It is thus possible that ERRF also plays a role in the development of ERBB2 positive breast cancer and its resistance to ERBB2-targeted therapies." (PMID 28415602, 2017). "Amplication of the ERBB2 gene or overexpression of ERBB2 protein was found in 30% of human breast carcinoma, and proved to result in poorer prognosis." (PMID 29163776, 2017). "Mice models with ERBB2-overexpressing breast carcinoma showed that CDK4/6 was pivotal to the maintenance of the disease." (PMID 28438180, 2017). "Despite the lack of success in the clinic, GM still plays fundamental roles as a potent HSP90 inhibitor for in vitro studies, especially in ERBB2+ breast cancer cells." (PMID 28914774, 2017). "In a proof-of-concept experiment, we assessed the cytotoxic capacity of WT and genetically modified CIK cells against the indicated ErbB2-overexpressing breast carcinoma cell line (MDA-MB-453) by europium release assay." (PMID 29029499, 2017). "As a molecular abnormality triggered by gene amplification, ERBB2 over-expression occurs in about 25 % of breast carcinomas and a subset of aggressive tumors." (PMID 28160563, 2017). "In solid tumors the response of ERBB2 gene amplified breast carcinomas to the anti-ERBB2 antibody trastuzumab is a further landmark in the development of targeted therapies." (PMID 28367253, 2017). "We evaluated the effect of chronic alcohol exposure on mammary tumor development/metastasis in MMTV-neu transgenic mice and investigated the cell signaling in response to alcohol exposure in breast cancer cells overexpressing ErbB2/HER2." (PMID 27416801, 2016). "In the early 2000′s, the ERBB2 targeting monoclonal antibody trastuzumab demonstrated significant improvements of survival in ERBB2-amplified breast cancer patients, leading to a “revolution” in medical oncology." (PMID 27602491, 2016). "We showed that in culture systems breast cancer cells overexpressing ErbB2 were much more sensitive to alcohol-induced migration/invasion compared to those cells with low expression of ErbB2." (PMID 27416801, 2016). "In human vulva cells, they target EGFR and in breast cancer cells they block the ErbB2/cSrc/FAK pathway and prevent their metastasis." (PMID 27877185, 2016). "Trastuzumab (Herceptin®) is an effective anticancer treatment for ErbB2-overexpressing breast cancer in the adjuvant, neo-adjuvant, and metastatic settings." (PMID 27596216, 2016). "We previously demonstrated that breast cancer cells overexpressing ErbB2 are much more sensitive to alcohol-induced migration/invasion compared to those cells with a low level of ErbB2." (PMID 27416801, 2016). "The dual-targeting TKI Lapatinib, which inhibits both EGFR and ErbB2, is approved for use in ErbB2 positive breast cancer upon relapse following treatment standard chemotherapy and trastuzumab." (PMID 27597943, 2016).
breast cancer (continued). "To investigate the relevance of the modulation of p130Cas expression in the control of ErbB2 stability we used, as an experimental model, ErbB2 positive BT474 breast cancer cells." (PMID 26716506, 2016). "Our findings support evidence demonstrating that growth factor receptors, such as insulin-like growth factor receptor (IGF-1R), EGFR, and ErbB2, play critical roles in the mediation of endocrine resistance in breast cancer." (PMID 27659519, 2016). "We then focused the comparison of CNAs on known driver oncogenes located within regions frequently amplified in breast cancer: ERBB2 (17q12), CCND1 (11q13.3), FGFR1 (8p11.23), MYC (8q24), and PAK1 (11q14.1)." (PMID 27028851, 2016). "The miR-125a-5p has been reported to be downregulated in male breast cancer patients with respect to tumor ErbB2 levels." (PMID 27992561, 2016). "Approximately 20–25% of breast cancers (BCa) have amplification/overexpression of human epidermal growth factor receptor 2 (ErbB2/Her2), a member of receptor tyrosine kinase family." (PMID 27050377, 2016). "As a comparison, it is worth noting that a prototypical oncogene driven by copy number amplification, ERBB2, shows a ρ = 0.63 in the same TCGA breast cancer dataset where SQLE was assessed." (PMID 26777065, 2016). "We have previously demonstrated that alcohol enhanced the migration/invasion of breast cancer cells and cancer cells overexpressing ErbB2/HER2 were more sensitive to alcohol exposure." (PMID 27416801, 2016). "Our recent studies identified the class I HDAC inhibitor entinostat (SNDX-275 or MS-275) as a special agent to selectively inhibit erbB3 leading to a dramatic reduction of P-Akt in erbB2-positive breast cancer cells." (PMID 26621843, 2016). "ErbB2 is often overexpressed in various malignancies, especially in breast cancer, and is a common target for anti-cancer drugs." (PMID 27542246, 2016). "For example, the EGFR kinase inhibitors gefitinib and erlotinib for non-small cell lung cancer patients; the EGFR/ERBB2 inhibitor lapatinib for ERBB2-positive breast cancer patients, and the VEGFR kinase inhibitor sorafenib for patients with renal cancer." (PMID 26751490, 2016). "These “repressed” genes include ESR1 (gene encoding ERα), ERBB2, GATA3, and ZNF217 —all critical genes to the etiology of breast cancer." (PMID 27539783, 2016). "Together, these results indicate that high expression of ErbB2 sensitizes breast cancer cells to alcohol exposure." (PMID 27416801, 2016). "Serum-starved ERBB2-positive SKBr3 breast cancer cells were exposed to EGF or heregulin (HRG) to activate HER2 through EGFR/HER2 and HER2/HER3 signalling routes, respectively." (PMID 27402251, 2016). "While tumor ERBB2 overexpression/gene amplification correlates with poor prognosis in breast cancer, similar studies in gastric cancer have been inconsistent." (PMID 26955870, 2016). "The key oncogenic role of ERBB2 amplification in a subset of breast cancer has been described in the late 80′s." (PMID 27602491, 2016). "In an effort to better identify patients more likely to achieve pCR in patients with ERBB2-positive breast cancer, we have evaluated a series of additional gene and centromere probes as well as Ki-67 expression." (PMID 27576528, 2016). "In summary, we found that in ErbB2-overexpressing breast cancer cells the ErbB2/Grb2 interaction leads to the direct activation of RAS which, in turn, mediates via interaction with p110α the p-AKT rebound in response to an incomplete blockade of ErbB2." (PMID 27255951, 2016). "Trastuzumab, an anti-HER2/ErbB2 humanized antibody, has shown great clinical benefits in ErbB2-positive breast cancer treatment." (PMID 27564098, 2016).